GLI1 (GLI family zinc finger 1)
Diseases named in the same sentence as GLI1 in open-access papers (continued):
Sharing a sentence is not in itself a finding about the gene and the disease.
breast carcinoma (continued). "The basal expression levels of GLI1 and GLI2 downstream of the Hh ligand in TNBC are higher than those in hormone receptor-positive (HR+) breast cancer, and the prognosis of breast cancer patients with high GLI1 expression is poor." (PMID 37700593, 2023). "The aim of this study was to evaluate the expression of SHH and GLI-1 in the serum and mammary tumour tissues of dogs." (PMID 37932728, 2023). "The Hh-GLI1 signaling pathway is activated and participates in the tumorigenesis and progression of breast cancer, especially in the aggressive subtype of triple-negative breast cancer (TNBC)." (PMID 36046646, 2022). "In the present study, we demonstrated aberrant overexpression of GLI1 in breast cancer tissues compared to that in normal breast tissues, especially in the TNBC subtype, suggesting a crucial role of the Hh-GLI1 signaling pathway in TNBC tumorigenesis." (PMID 36046646, 2022). "The co-overexpression and physical interaction of phospho-STAT3 and GLI1, the glioma-associated oncogene, is found in approximately 60–70% of both TNBC and HER2-enriched breast cancers." (PMID 35053592, 2022). "We previously published the discovery of the novel gain-of-function GLI1 transcription factor, tGLI1, and its role in breast cancer progression and metastasis." (PMID 36077791, 2022). "For example, a combination therapy of the STAT3 inhibitor (STX-0119) and GLI1/tGLI1 inhibitor has been investigated as a breast cancer treatment strategy." (PMID 35158821, 2022). "In conclusion, this study indicates that targeting GLI1 reprograms the tumor glucose metabolism to suppress breast cancer cell growth and proliferation." (PMID 36046646, 2022). "Deviating transcriptional upregulation of GLI1 is seen downstream of NF-κB in claudin-low breast cancer, a sub-type of TNBC." (PMID 35744786, 2022). "GLI1 protein expression was localized in both the nucleus and cytoplasm and was significantly higher in breast cancer tissues than in normal tissues." (PMID 36046646, 2022). "In stark contrast to GLI1, tGLI1 expression is tumor-specific: tGLI1 is frequently expressed in glioblastomas, primary and metastatic breast carcinomas, and breast cancer cell lines, but is undetectable in normal mammary, brain, and other tissues." (PMID 36077791, 2022). "GLI1 was highly expressed in all the breast cancer cell lines, with the lowest expression observed in MDA-MB-453 cells." (PMID 36046646, 2022). "GLI1 expression was examined in 74 breast cancer tissues and compared with the expression in nine normal breast tissues based on molecular subtypes and tumor stages." (PMID 36046646, 2022). "GLI1/tGLI1 is overexpressed and it is an important protein for maintaining the proliferation and anti-apoptosis of breast cancer stem cell self-renewal." (PMID 35158821, 2022). "To confirm that GLI1 inhibition can affect the cytotoxicity of breast cancer cells, we compared the cytotoxicity of MDA-MB-231 cells treated with a specific GLI1 inhibitor, GANT61." (PMID 36046646, 2022). "A meta-analysis done in few studies explained GLI1 expression as one of the factors in aggressive biological behavior in breast cancer patients." (PMID 33494284, 2021). "Truncated GLI1 activates the metastasis-initiating cancer stem cells and astrocytes in the breast cancer microenvironment and promotes its metastasis to the brain." (PMID 33499351, 2021). "Dose-dependent GLI1 mRNA induction was also observed in human pancreatic cancer cells (AsPC1), in human breast carcinoma cells (MCF7), and in human embryonic kidney cells (Hek293A)." (PMID 33921042, 2021). "We showed that treatment of MDA-MB-231 breast cancer cells with GLI1 siRNA induced inhibition of mammosphere formation and down-regulation of YAP1, a Hippo pathway effector." (PMID 34445421, 2021). "Although expressed in many subtypes of breast cancer, GLI1 preferentially promotes growth of ER-negative breast cancer cells and is associated with poorer survival with TNBC compared to ER-positive disease." (PMID 34889737, 2021).
breast carcinoma (continued). "Particularly, FGFR1 and GLI1 showed strong correlation with late stage, node, and metastasis in luminal subtypes of breast cancer patients." (PMID 34722544, 2021). "GLI1 overexpression in breast cancer serves as a significant marker of aberrant activation of the SHH pathway driving the formation and progression of breast cancer." (PMID 33494284, 2021). "Investigation of the mechanism revealed that overexpression of SET7/9 inhibited GLI1 expression, suggesting that GLI1 expression in human breast cancer tissues negatively correlates with SET7/9 expression." (PMID 33494284, 2021). "Combined exposures to AZD4547 (FGFR1 inhibitor) and GANT61 (GLI1 inhibitor) significantly reduced cell proliferation, cell motility, and invasion, suggesting molecular crosstalk in breast cancer progression and metastasis." (PMID 34722544, 2021). "The dysregulation of Hedgehog signaling, including GLI1 upregulation, is frequently reported in young breast cancer patients with shorter overall survival." (PMID 34722544, 2021). "Herein, we reported a different mechanism by which coexpression of FGFR1 and GLI1 genes leads to breast cancer invasion and metastasis." (PMID 34722544, 2021). "tGLI1 has been reported as a stronger promoter of tumor migration and invasion as compared to GLI1 in glioblastoma and breast cancer." (PMID 33494284, 2021). "Previous studies have reported a breast cancer subtype-specific relationship between GLI1 and various aspects of stemness and metastatic progression." (PMID 34889737, 2021). "Together, these results establish that SET7/9 inhibits oncogenic activities by regulating GLI1 expression in breast cancer." (PMID 33494284, 2021). "In breast cancer, Gant61 treatment decreased cell proliferation by reducing GLI1 and PTCH1 gene expression and inhibited GLI1 nuclear translocation." (PMID 33396427, 2020). "Another study showed that a C-terminal binding protein (CtBP)-dependent transcriptional repressor TSHZ2 of GLI1 is downregulated in breast cancer cell lines leading to overexpression of GLI-target genes such as CXCR4." (PMID 33096815, 2020). "TSHZ2 (zinc-finger homeobox protein) was shown to be a transcriptional repressor that is downregulated in breast cancer cells and to exert negative regulation on Gli1 activity in normal and immortalized mammary gland duct epithelium." (PMID 32565808, 2020). "Overexpression of Hedgehog molecules SMO and GLI1 exists in breast cancer and mammary hyperplasia, which can affect histological grade or tumor stage in TNBC." (PMID 32962123, 2020). "Recently, studies of estrogen receptor (ER)-positive breast cancer (BC) cell lines have revealed that estrogen can increase GLI1 and GLI2." (PMID 31979397, 2020). "GLI1, a terminal effectors of the HH factors, was reported to serve as an oncogene in wide ranges of cancers, such as breast cancer, CRC, prostate cancer, glioma, pancreatic cancer, gastric cancer, and cervical cancer." (PMID 32793474, 2020). "The present study was conducted to explore the influence of SHH/GLI1 axis on epithelial mesenchymal transition and invasion in breast cancer cells." (PMID 31036836, 2019). "Current findings provide firm evidence of involvement of SHH/GLI1 axis in augmenting EMT signals in breast cancer cells." (PMID 31036836, 2019). "GANT61 caused a significant reduction in cell proliferation, motility and invasion in GLI1 over expressing breast cancer cell lines." (PMID 31394751, 2019). "For example, tumor necrosis factor alpha (TNF-α) and interleukin-1β (IL-1β) can upregulate the expression of GLI1 through the nuclear factor kappa light chain enhancer of activated B cells (NF-κB) pathway in pancreatic and breast cancer cells." (PMID 30759860, 2019). "It is thereby inferred that SHH/GLI1 axis enhances invasiveness by potentiating the expression of EMT markers in breast cancer cells." (PMID 31036836, 2019).
breast carcinoma (continued). "As in other studies, estrogen increased GLI1 expression and %GLI1 nuclear translocation and invasiveness of HR+ breast cancer cells." (PMID 31394751, 2019). "Our group also identified co-expression of GLI1 and two GLI1 targets, EGFR and SNAI1, to be associated with worse disease-free survival in HR breast cancer." (PMID 31394751, 2019). "In conclusion, data suggest that GLI1 reciprocates SHH in breast cancer cells and GANT61 is effectual in curtailing cell viability in dose and time dependent manner." (PMID 31036836, 2019). "On the contrary, E-cadherin was negatively related to the Hedgehog mediators in the cohort showing the potential involvement of SHH/GLI1 in breast cancer progression." (PMID 31036836, 2019). "In order to understand association between altered expression of SHH/GLI1 axis and EMT markers in breast cancer cohort, immunostaining and qRT-PCR was performed." (PMID 31036836, 2019). "In the present study, correlation of SHH/GLI1 axis with EMT markers was assessed in breast cancer cohort." (PMID 31036836, 2019). "We noted a consistent increase in the expression of SHH, SMO and GLI1 that correlated with the level of tamoxifen resistance in breast cancer cell lines." (PMID 31394751, 2019). "GANT61 is a small GLI1 antagonist that was also reported to have antitumor activity in breast cancer." (PMID 30423843, 2018). "GLI1AS expression showed high positive correlation with GLI1 expression in basal cell carcinoma and breast cancer." (PMID 30158435, 2018). "Knockdown of IGF2BP1 in colorectal and breast cancer cell lines using the RNAi approach significantly lowered GLI1 expression in these cells." (PMID 29987229, 2018). "Even though the tGLI1 mechanism of action was different from that of GLI1, it functioned similarly in promoting breast cancer growth." (PMID 30423843, 2018). "New studies have suggested that the expression of Gli1 is related to prognosis in HER2 positive breast cancer, and Gli1 is regulated by HER2 via PI3K-Akt pathway in esophageal adenocarcinoma." (PMID 29321573, 2018). "Early evidence demonstrated the overexpression of GLI1 in breast cancer cell lines as well as primary breast carcinoma." (PMID 30018256, 2018). "Accordingly, a direct binding of the NFκB transcriptional complex to the GLI1 promotor region has been observed, and inhibition of NFκB decreased GLI1 expression in breast cancer cells." (PMID 29695137, 2018). "GLI1 inhibitors such as pirfenidone and imiquimod have been reported to have promising antitumor activity in breast cancer." (PMID 30423843, 2018). "It is interesting to note that BIO can activate Gli1 transcription in human breast cancer cells, and GSK3 is known to silence Hh signaling by phosphorylating the Drosophila GLI homolog, Cubitus interruptus (Ci) following priming by PKA." (PMID 29119099, 2017). "Some studies have indicated that over-expression of Gli1 predicted poor outcome of breast cancer with higher tumor stage and increased number of tumor-positive axillar lymph nodes." (PMID 29113369, 2017). "We found strong positive correlations between SIX1, SNAI1 or TWIST1 with GLI1 (a Hh pathway target) in numerous breast cancer data sets." (PMID 28604738, 2017). "Gli1 overexpression is revealed to have a close connection with breast cancer as a significant maker of aberrant activation of SHH pathway." (PMID 29113369, 2017). "The breast cancer with nuclear Gli1 over-expression signified early relapse after radical operation, therefore mammary gland color ultrasound is particularly necessary in patient reexamination." (PMID 29113369, 2017). "It integrated convincing evidence to elucidate relationship between Gli1 expression and prognosis of breast cancer." (PMID 29113369, 2017). "Our meta-analysis is the first one to explain Gli1 expression as an aggressive biological behavior in breast cancer patients." (PMID 29113369, 2017).
breast carcinoma (continued). "Result showed Gli1 over-expression was correlated with shorter DFS in breast cancer patients (HR = 1.38, 95% CI: [1.05, 1.81])." (PMID 29113369, 2017). "Survival outcomes of breast cancer with high and low Gli1 expression from 6 studies were extracted and analyzed." (PMID 29113369, 2017). "In the past, numerous reports suggest that Gli1 is a biomarker of invasion, metastasis, or prognosis in various types of cancer, including lung squamous cell carcinoma, glioblastoma, breast cancer, colorectal cancer and pancreatic adenocarcinoma." (PMID 29375376, 2017). "So the clinical staff should pay more attention to patients with breast cancer with high Gli1 expression in systemic screening, such as increasing the frequency of bone scan." (PMID 29113369, 2017). "Nevertheless, it was remarkable that we confirmed that breast cancer patients with over-expression of Gli1 tended to obtain a worse survival outcome referring to DFS, 3-year survival, 5-year survival and OS." (PMID 29113369, 2017). "An increased expression of Shh and Gli1 in human breast cancer supports the notion that dysregulation in Hh signaling promotes breast cancer development and progression." (PMID 26727947, 2016). "We observed that high GLI1 expression is associated with poor distant metastasis-free survival (DMFS) in 126 patients with Grade 1, ERα-positive breast cancer." (PMID 27689403, 2016). "Here, we analyzed GLI1, Sonic Hedgehog (Shh) and NF-κB expression in 51 breast cancer (ductal carcinoma) tissues using immunohistochemistry." (PMID 26843616, 2016). "It would be interesting but also challenging to verify GLI1 as prognostic marker in a larger number of patients and/or other subtypes of breast cancer." (PMID 27689403, 2016). "An additional pathway that can interact with HH signaling in breast cancer is TGFβ, which induces transcriptional up-regulation of GLI1 and GLI2." (PMID 27548161, 2016). "In a cohort of 315 patients with breast cancer, high GLI1 expression inversely correlated with disease-free and overall survival." (PMID 27548161, 2016). "Then, we examined the effects of NC on mRNA expression of Gli1 and Smo by RT-PCR in breast cancer cell line MDA-MB-468 and MCF-7." (PMID 27313840, 2016). "We have shown that tGLI1 is a gain-of-function GLI1 that has a higher propensity than GLI1 to induce aggressive cancer phenotypes in both breast cancer and glioblastoma, including, growth, invasion, migration, and angiogenesis." (PMID 26891329, 2016). "To explore the clinical relevance of the effect of GLI1 on ERα signaling and breast cancer, we examined the expression of GLI1, ESR1 (the gene encoding ERα) and known ERα target genes in a dataset of breast cancer samples from 286 individuals." (PMID 27689403, 2016). "In ERα-positive breast cancer cells, estrogen was found to act via GLI1, promoting the development of cancer stem cells and epithelial to mesenchymal transition." (PMID 27689403, 2016). "Recently, activation of Wnt signaling in metastatic breast cancer cells was shown to induce expression of PTHrP through the Gli1 transcription factor." (PMID 27738322, 2016). "To investigate the role of ERα and GLI1 in breast cancer cell proliferation, we transfected MCF7 and LCC2 cells with siRNAs targeting ERα or GLI1." (PMID 27689403, 2016). "Taken together, in this work we have demonstrated that tamoxifen cytotoxicity can be enhanced by blockade of the HH pathway, reflecting a cross-talk between ERα and GLI1 signaling, both in tamoxifen resistant and sensitive breast cancer cells." (PMID 27689403, 2016). "Our current results indicate that GLI1 is expressed to a higher extent in tamoxifen resistant compared to sensitive breast cancer cells." (PMID 27689403, 2016). "Alternatively, several studies reported overexpression of Hh ligands, often Shh, and of the Hh transcriptional targets GLI1 and Ptch1 and, thus, the activation of the Hh pathway in breast cancer." (PMID 26843616, 2016).
breast carcinoma (continued). "Conversely, several studies reported the overexpression of an Hh ligand, often Shh, and the Hh transcriptional targets GLI1 and Ptch1, thus activating the Hh pathway, in breast cancer." (PMID 26843616, 2016). "Then we examined the prognostic role of GLI1 expression for breast cancer patients using the Kaplan-Meier Plotter dataset." (PMID 27689403, 2016). "Our data indicate that GLI1 depletion reduces the proliferation of both tamoxifen resistant and sensitive breast cancer cells." (PMID 27689403, 2016). "Our studies revealed a novel mechanism involving NC targeting breast cancer metastasis, in which inactivation of Hedgehog signaling pathway by NC treatment led to a significant decreased expression of Smo and Gli1." (PMID 27313840, 2016). "Consistently, transgenic mice that conditionally expressed GLI1 in the mammary epithelium developed mammary tumors." (PMID 27689403, 2016). "Shh, and its ligands, expression are correlated with ER-alpha breast cancers, while Smo and Gli-1 are overexpressed in TNBC." (PMID 26389956, 2015). "They, and others, have observed increased nuclear localization of Gli-1 in breast cancer samples compared to normal breast tissue, yet there was agreement in two studies that strength of expression of Gli-1 varied significantly among breast cancer samples." (PMID 26389956, 2015). "In breast cancer, the increased expression of GLI1 correlated with metastasis and unfavorable overall prognosis, though its molecular mechanism is also not fully understood." (PMID 26413813, 2015). "Expression of Shh, Ptch-1, Gli-1, and Smo mRNA in breast cancer tissue was also shown to correlate with disease recurrence." (PMID 26389956, 2015). "These evidences provide insight into the molecular mechanism that explains why GLI1 expression and CXCR4/CXCR7 axis are both linked to a poor prognosis of breast cancer patients." (PMID 26413813, 2015). "Downregulation of GLI1 in the ErbB1/2-resistant breast cancer cells reduced proliferation, increased apoptosis and decreased migration." (PMID 26633513, 2015). "These evidences experimentally indicated that the activity of GLI1 contributed to the increased metastatic potential of breast cancer cells." (PMID 26413813, 2015). "Further evidence for differing Hh patterns within the different breast cancer subgroups was illustrated by the finding of Gli-1 and Smo overexpression in TN breast cancer cases and a positive correlation with increased tumor stage." (PMID 26389956, 2015). "Assuming therefore that GLI1 up-regulates a set of these CXCL12-related signaling components in breast cancer cells, we focused our study on CXCR4, CXCR7 and LCP1." (PMID 26413813, 2015). "A study suggested that the mRNA of Ptch-1 and Gli-1 in core needle biopsy would provide a useful tool for surgeons and patients for the selection of treatment options in the clinical management of breast cancer." (PMID 26389956, 2015). "It has also been reported that it was not only Gli-1 that was important for breast cancer prognosis but also that there was increased expression of Shh which has been shown to contribute to tumor cell survival." (PMID 26389956, 2015). "To elucidate the role of GLI1 in breast cancer metastasis, we started with the experiments of lung metastasis using Balb/c mouse-derived breast cancer cells of 4T1-Luc, a derivative of 4T1 cells in which luciferase was stably transduced." (PMID 26413813, 2015). "High levels of SMO and Gli-1 expression have been found to correlate with continuous activation of breast cancer stem cells in TNBC patients samples." (PMID 26389956, 2015). "The promoter region of the HH gene was found to be hypo-methylated in breast cancers and this correlated with increased HH and nuclear factor (NF)-kB expression, and nuclear accumulation of GLI1." (PMID 26633513, 2015).